HGF (hepatocyte growth factor)
Diseases named in the same sentence as HGF in open-access papers (continued):
Sharing a sentence is not in itself a finding about the gene and the disease.
diabetic foot ulcers (1 paper, 2021). "Therefore, recombinant HGF has been proposed for the treatment of diabetic foot ulcers." (PMID 34440227, 2021).
diabetic macular edema (1 paper, 2024). "In diabetic macular edema (DME), vascular endothelial growth factor (VEGF), hepatocyte growth factor (HGF), IL-6, and MCP-1 increase vascular permeability and promote angiogenesis in DR." (PMID 39634174, 2024).
dilated (1 paper, 2008). "For example, adenovirus-mediated HGF gene transfer before ischemia led to decreased fibrosis, and treatment of dilated cardiomyopathic Syrian hamsters with HGF for three weeks suppressed cardiac fibrosis and led to a decrease in TGF-β1 and type I collagen expression." (PMID 19014650, 2008).
Disseminated intravascular coagulation (1 paper, 2023). Disseminated intravascular coagulation is characterized by the widespread activation of coagulation, which results in the intravascular formation of fibrin and ultimately thrombotic occlusion of small and midsize vessels. "Hepatocyte growth factor (HGF) is a marker that plays a role in the prevalence of disseminated intravascular coagulation (DIC)." (PMID 37504277, 2023). "HGF regulates the upregulation of pro-coagulation factors (PAI-1&COX-2), which trigger disseminated intravascular coagulation (DIC)." (PMID 37504277, 2023).
dysplasia (1 paper, 2017). A usually neoplastic transformation of the cell, associated with altered architectural tissue patterns. "Increased transforming growth factor β1 (TGFβ1) and hepatocyte growth factor (HGF) have been linked to the progression from dysplasia to ESSC." (PMID 29204834, 2017).
endometrioid tumor (1 paper, 2020). A benign, borderline, or malignant epithelial tumor of the female reproductive system characterized by the presence of glands and/or cysts lined by neoplastic cells that resemble endometrial cells. "Expression of γ-H2A.X foci, which was elevated after exposure to ascites from endometrioid tumors, was reduced by the inhibition of HGF." (PMID 32012719, 2020).
endotoxemia (1 paper, 2018). "Additionally, it has been observed to upregulate hepatocyte growth factor (HGF) and matrix metalloproteinases (MMPs), downregulate tissue inhibitor of metalloproteinase 1 (TIMP-1), reduce portal pressure, bacterial translocation and endotoxemia." (PMID 29702590, 2018).
erysipelas (1 paper, 2017). An infection of the upper layers of the skin caused by species of streptococcus. "Interestingly, we have found increased serum level of HGF in erysipelas with C/C genotype of SOD2 C2734T." (PMID 28512644, 2017).
fibrous tumor (1 paper, 2020). "Causes of clubbing of the fingers and toes and of hypertrophic pulmonary osteoarthopathy are as follows: an abnormal production of hepatocyte growth factor (HGF) or a high level of hyaluronic acid, secreted by the fibrous tumor." (PMID 32316178, 2020).
Fuchs' endothelial dystrophy (1 paper, 2024). Fuchs endothelial corneal dystrophy (FECD) is the most frequent form of posterior corneal dystrophy and is characterized by excrescences on a thickened Descemet membrane (corneal guttae), generalized corneal edema, with gradually decreased visual acuity. "Future in vivo studies are warranted to further explore the clinical applicability of HGF in treating corneal endothelial dysfunction, particularly in conditions like Fuchs’ endothelial dystrophy (FED), where donor tissue availability remains a critical challenge." (PMID 39273330, 2024).
gallbladder cancer (1 paper, 2013). "HGF induces invasion and migration of the gallbladder cancer cells in Matri-gels, while NK4 inhibits HGF-induced invasion." (PMID 23296269, 2013).
gastric adenocarcinoma (1 paper, 2016). "The previous reports showed that Ki-67, c-Met, vascular endothelial growth factor (VEGF), STAT3, hepatocyte growth factor and its receptor were highly expressed in AFP producing gastric adenocarcinoma tissues and cell lines as compared with AFP-negative gastric adenocarcinoma." (PMID 27057629, 2016).
gastroenteritis (1 paper, 2005). An inflammatory disorder that affects the upper and lower gastrointestinal tract. "Determination of HGF by SPR might be beneficial in diagnosis of acute situations that present with symptoms of gastroenteritis and may, possibly, guide appropriate medical treatments." (PMID 15826299, 2005).
GEJ adenocarcinoma (1 paper, 2016). "In a randomized placebo-controlled phase II study, the efficacy of the anti-HGF antibody rilotumumab was evaluated in combination with platinum-based chemotherapy as first-line treatment in patients with advanced gastric or GEJ adenocarcinoma." (PMID 26716644, 2016). "Recently, two large-scale randomized phase III trials (RILOMET-1 study: rilotumumab, MetGastric study: onarutuzumab) evaluated the efficacy of adding HGF/MET inhibitor to first-line chemotherapy in MET-positive patients with unresectable gastric or GEJ adenocarcinoma." (PMID 26716644, 2016).
giant cell tumour (1 paper, 2023). "However, in giant cell tumour of the bone, it has been shown that there are other growth factors like vascular endothelial growth factor (VEGF) and hepatocyte growth factor (HGF), that stimulate osteoclastogenesis, even in the absence of M-CSF." (PMID 37509363, 2023).
glomerulonephritis (1 paper, 2006). A renal disorder characterized by damage in the glomeruli. "HGF gene transfection effectively prevented the proteinuria and histopathological changes associated with glomerulonephritis." (PMID 16859527, 2006).
Graves disease (1 paper, 2016). Graves' disease is an autoimmune disorder that leads to overactivity of the thyroid gland (hyperthyroidism).It is caused by an abnormal immune system response that causes the thyroid gland to produce too much thyroid hormones. "Serum HGF and IL-8 concentrations are elevated in Graves’ disease patients with active Graves’ orbitopathy as compared to the healthy control group." (PMID 26062519, 2016). "However, to the best of our knowledge, our study is the first to evaluate HGF concentration in Graves’ disease patients with clinically active GO." (PMID 26062519, 2016).
Graves’ orbitopathy (1 paper, 2016). "Successful management of active Graves’ orbitopathy with glucocorticoids is associated with a decrease in HGF and IL-8 serum concentrations." (PMID 26062519, 2016).
hematoma (1 paper, 2026). A hematoma is a collection of blood from a vascular structure into an extravascular space. "In a clinically relevant rat model of ICH with hematoma evacuation, the combined therapy of HGF and SVF demonstrated synergistic and enhanced efficacy." (PMID 41892579, 2026).
hemorrhagic fever (1 paper, 2017). An infectious disease caused by certain viruses or bacteria that can damage the walls of tiny blood vessels, making them leak, and can hamper the blood's ability to clot and cause severe, life-threatening illness. "Hemorrhagic fever with renal syndrome cases were characterized by a strong expression of MIF, IL-12p40, IL-3, IL-16, CXCL9, CCL27, CXCL1, and HGF." (PMID 28572804, 2017).
hepatitis B (1 paper, 2024). "Furthermore, we found that IL-5 and HGF were promising predictors for predicting the immunization response to hepatitis B vaccine in infants, and the combination of the two cytokines showed the best predictive efficiency, with an area under the curve (AUC) value of 0.844." (PMID 38495649, 2024). "There are few studies on the mechanisms of HGF, IL-12p40 and β-NGF in the immune response to hepatitis B vaccine." (PMID 38495649, 2024).
hereditary cardiomyopathy (1 paper, 2019). "HGF is highly relevant in tissue fibrosis and remodeling as investigated in an in vivo model, in which Syrian hamsters suffering from hereditary cardiomyopathy were treated with HGF." (PMID 31402914, 2019).
Hereditary papillary renal carcinoma (1 paper, 2011). "Hereditary papillary renal carcinoma (HRPC) is associated with activating mutations in the MET gene on chromosome 7; this oncogene encodes a membrane tyrosine kinase receptor whose ligand is hepatocyte growth factor (HGF)." (PMID 22738081, 2011).
HIV-1 infection (1 paper, 2016). The type species of lentivirus and the etiologic agent of acquired immunodeficiency syndrome (AIDS). "In a co-culture study of HIV-1 infected T cells (CEM) and latently KSHV infected B cells (BCBL-1), several cytokines including oncostatin M (OSM), hepatocyte growth factor/scatter factor (HGF/SF), and IFN-γ were found to be induced in response to HIV-1 infection in CEM or BCBL-1 cells." (PMID 26913028, 2016).
Hyperoxaluria (1 paper, 2019). Increased excretion of oxalates in the urine. "RSG can regulate TGF-β1 and HGF/c-Met through PPAR-γ to exert antioxidant effects against hyperoxaluria and alleviate crystal deposition." (PMID 31781338, 2019).
hypopharyngeal carcinoma (1 paper, 2018). Carcinoma, predominantly squamous cell, arising from the epithelial cells of the hypopharynx. "Finally, it has been also shown that EGCG blocked HGF-induced invasion and metastasis of hypopharyngeal carcinoma cells." (PMID 29760813, 2018).
Impaired glucose tolerance (1 paper, 2022). An abnormal resistance to glucose, i.e., a reduction in the ability to maintain glucose levels in the blood stream within normal limits following oral or intravenous administration of glucose. "The obtained results made HGF/VEGF combined plasmid a very promising tool for PAD therapy in impaired glucose tolerance conditions." (PMID 36497083, 2022).
inflammatory breast carcinoma (1 paper, 2024). An advanced, invasive breast adenocarcinoma characterized by the presence of distinct changes in the overlying skin. "Zoratti found that the serine protease ST14 specifically cleaves the inactive pro-form of the hepatocyte growth factor (pro-HGF), promotes the release of HGF, binds c-Met, and then promotes the proliferation and invasion of inflammatory breast cancer cells." (PMID 38468232, 2024).
inflammatory demyelinating neuropathy (1 paper, 2019). "CXCL13 appears to be more specific for representing inflammatory demyelinating neuropathy compared with the previously demonstrated cytokines such as HGF, TNF-α and CCLs for several reasons." (PMID 31712675, 2019).
Kidney Cyst (1 paper, 2024). Abnormal fluid filled sac within the kidney, either acquired or congenital. "Furthermore, kidney cysts treated with hepatocyte growth factor (HGF) release EVs containing G protein-coupled receptor 5B (GPRC5B), which, in conjunction with HGF, promotes renal tubulogenesis." (PMID 39439545, 2024).
kidney injury (1 paper, 2015). Trauma to the kidney. "It is well recognized that MSCs can secrete a broad range of trophic factors, such as HGF, bFGF, IGF-1, and EGF, all known to improve the renal function in animal models of kidney injury, due to their antiapoptotic, mitogenic, and morphogenic activities on intrarenal cells." (PMID 26167475, 2015).
kidney stone (1 paper, 2019). "The imbalance between TGF-β1 and HGF/c-Met leads to the accumulation of ROS and related protein damage, which becomes the initial event in the development of nephrolithiasis." (PMID 31781338, 2019). "PPAR-γ is upstream of the HGF/c-Met signaling pathway and can regulate the activation of Smad7; therefore, we determined whether PPAR-γ regulates the expression of HGF, c-Met, and Smad7 in renal tubular epithelial cells during kidney stone formation." (PMID 31781338, 2019).
Legionella pneumonia (1 paper, 2011). "Further studies that investigate the precise role of HGF in severe Legionella pneumonia are warranted." (PMID 21429184, 2011). "In this study, in order to clarify the role of HGF in Legionella pneumonia, the serum HGF concentrations in patients with Legionella pneumonia as well as other pulmonary infections were determined." (PMID 21429184, 2011). "Our study aimed to determine the role of serum HGF levels in Legionella pneumonia." (PMID 21429184, 2011). "Present study revealed that in patients with Legionella pneumonia, serum HGF levels were higher in non-survivors than in survivors." (PMID 21429184, 2011). "The male predominance of Legionella pneumonia did not influence the HGF levels." (PMID 21429184, 2011).
leukopenia (1 paper, 2024). "Transcriptomics results showed changes in the expression of JUN, FOS, and HGF genes in both the model group and the QJSB group, further supporting the potential role of QJSB in regulating cell growth processes for the treatment of leukopenia." (PMID 39295929, 2024).
leukoplakia (1 paper, 2017). A white patch or plaque on a mucous membrane that cannot be characterized clinically or pathologically as any other disease. "Notably, several sub-branches of ILK, IGF1R, HIF1, HGF, MAPK and WNT pathways were among the most differentially dysregulated axes between OSCC and leukoplakia, suggesting their role in the transition from non-invasive to invasive disease." (PMID 28580171, 2017).
Lipedema (1 paper, 2023). Disorder of adipose tissue characterized by symmetric and bilateral enlargement of the lower extremities due to abnormal deposition of subcutaneous fat often in obese women. "Interestingly, HUVECs treated with ASCL CM showed a 2-fold increase in the expression of the HGF gene compared to untreated cells, suggesting that CM media from lipedema ASCs might instigate angiogenesis." (PMID 37686378, 2023). "Furthermore, HUVECs treated with ASCL CM showed the increased expression of the HGF gene compared to ASCH CM-treated and untreated cells, suggesting that CM media from lipedema ASCs might also instigate angiogenesis." (PMID 37686378, 2023).
liposarcoma (1 paper, 2015). A usually painless malignant tumor that arises from adipose tissue. "Notably, none of the more than 150 liposarcoma samples of any type (i.e., atypical lipomatous tumor, dedifferentiated, myxoid and pleomorphic liposarcoma) showed MET amplification, MET copy number gain or MET or HGF overexpression." (PMID 25844809, 2015).
lung squamous cell carcinomas (1 paper, 2023). "Accordingly, a recent study has reported high levels of HGF transcripts in lung squamous cell carcinomas expressing or not METex14." (PMID 36799689, 2023).
lymphangioma (1 paper, 2007). A benign lesion composed of dilated lymphatic channels. "In contrast to BECs, LECs seem to be highly responsive to stimulation with hepatocyte growth factor (HGF), but we could not detect significant expression of the HGF receptor, c-Met, in lymphangioma LECs as compared to HUVECs." (PMID 17584927, 2007).
lymphatic disease (1 paper, 2014). "Furthermore, these analyses shows that in this large extended family, lymphatic abnormalities are more severe and of earlier onset in individuals with additional mutations in genes that have been associated with lymphatic disease previously, such as HGF, or within MAPK/ERK signaling pathway." (PMID 25383712, 2014).
macular degeneration (1 paper, 2024). Loss of vision in the central portion of the retina (macula), secondary to retinal degeneration. "Additionally, MIG (OR: 1.0076, 95% CI: 1.0031–1.0122, p = 0.0009) and hepatocyte growth factor (HGF, OR: 0.9912, 95% CI: 0.9844–0.9979, p = 0.0106) were associated with the risk of macular degeneration." (PMID 38327497, 2024). "Our study further supports these previous studies, highlighting HGF as a protective factor in the development of macular degeneration." (PMID 38327497, 2024).
macular edema (1 paper, 2022). "On the other hand, the aqueous levels of HGF correlate with macular edema severity; it was increased in the cells and macrophages associated with retinal neovascularization in the murine model of an ischemic retina." (PMID 36291965, 2022).
malignant meningiomas (1 paper, 2021). "The c-MET inhibitor (SU11274) and the PI3K inhibitor (LY294002) suppressed HGF-induced migration, invasion, and EMT of human malignant meningioma cells." (PMID 34408780, 2021). "HGF and c-MET were found to be positively expressed in both benign and malignant meningiomas and were both localized in the cell membrane and cytoplasm." (PMID 34408780, 2021).
meningitis (1 paper, 2015). A disorder characterized by acute inflammation of the meninges of the brain and/or spinal cord. "The aim of the present study was to assess whether HGF concentrations and HGF binding affinity for its receptors might serve as markers to distinguish between meningitis associated with neurosurgery and other causes of infection." (PMID 26408034, 2015). "However, in the previous study we have reported intrathecal production of HGF during septic meningitis." (PMID 26408034, 2015). "Compared to samples from patients that had undergone neurosurgery and had other infectious diseases, CSF samples from patients with nosocomial meningitis had significantly higher HGF concentrations (p < 0.001) and binding affinity to c-Met (p < 0.001) and HSPG (p = 0.043) receptors." (PMID 26408034, 2015). "The present study focused on nosocomial meningitis in assessing the levels of HGF in the CSF." (PMID 26408034, 2015). "The HGF concentration and binding affinity to HGF receptors were significantly higher in CSF from patients with community-acquired septic meningitis compared to patients with aseptic (viral and subacute) meningitis as well as controls (p < 0.001)." (PMID 26408034, 2015). "In febrile nosocomial infections that occurred post neurosurgery, HGF assessment could substantially improve the differentiation of meningitis from other infections and therefore might be a tool for rapid diagnosis, limiting injuries and guiding antibiotic therapy." (PMID 26408034, 2015). "The results show a significantly higher CSF HGF levels in nosocomial septic meningitis compared to other nosocomial infections in the post- neurosurgery patients that had low correlation to the number of cells in CSF." (PMID 26408034, 2015).
muscle atrophy (1 paper, 2018). "Therefore, HGF may be able to produce multiple effects in various diseases associated with muscle atrophy following denervation." (PMID 30195792, 2018).
myopic maculopathy (1 paper, 2025). "Among the biomarkers analyzed, HIF-1α and HGF exhibited the strongest correlations with clinical parameters, indicating their potential association with axial elongation and myopic maculopathy, within a complex interplay of hypoxia, inflammation, and structural ocular changes." (PMID 41438149, 2025).
neck cancer (1 paper, 2015). "A separate pool of cells isolated from the head-and-neck cancer biopsy were stimulated with a growth factor cocktail of EGF/ HGF/IGF1 and demonstrated response along pAKT, pERK and pSTAT5 pathways." (PMID 25807104, 2015).
nephromegaly (1 paper, 2013). "In addition, the ratio of plasma HGF/TGF-β1 during the acute phase and after the recovery phase correlated positively with the degree of nephromegaly in all patients with KD." (PMID 24288547, 2013). "The reciprocal change between HGF and TGF-β1 may suggest a decreased antiproliferative effect of TGF-β1 on renal growth and also potentiate the mitogenic action of HGF, leading to nephromegaly in patients with KD." (PMID 24288547, 2013).
nephrotic syndrome (1 paper, 2025). A collection of symptoms that include severe edema, proteinuria, and hypoalbuminemia; it is indicative of renal dysfunction. "Reduced levels of HGF, a growth factor with anti-apoptotic and pro-survival effects on podocytes, have been associated with the progression of nephrotic syndrome." (PMID 39996798, 2025).
neuroendocrine tumours (1 paper, 2014). "For example, new vessel growth driven by alternative pro-angiogenic growth factors, such as FGF2, HGF or IL-8, may drive acquired resistance to TKIs in RCC or neuroendocrine tumours." (PMID 24482243, 2014).
neurofibroma (1 paper, 2020). An intraneural or extraneural neoplasm arising from nerve tissues and neural sheaths. "Previously, our genomic analysis of human MPNST progression revealed that MET and HGF copy number gains are present at the earliest stage of neurofibroma transformation and increase during metastasis and resistance." (PMID 32245042, 2020).